PPARA (peroxisome proliferator activated receptor alpha)
Diseases named in the same sentence as PPARA in open-access papers (continued):
Sharing a sentence is not in itself a finding about the gene and the disease.
oral cancer (13 papers, 2016 to 2024). "In this study, we found that PPARα protein levels were negatively associated with tumor development in an oral cancer mouse model." (PMID 26869356, 2016). "In contrast, previous research showed that HMGCS2 enhances invasion and metastasis by directly interacting with PPARα to activate Src signaling in colorectal and oral cancers." (PMID 38923428, 2024). "A previous study reported that CompC reduced the anti-invasive effect induced by fenofibrate, a peroxisome proliferator-activated receptor alpha (PPARα) agonist and a lipid-lowering agent, in human oral cancer CAL 27 cells in an AMPK-dependent manner." (PMID 36077072, 2022). "In this study, we used a pathway-based strategy to identify possible functional pathways involved in the anticancer activity of PPARα in oral cancer cells." (PMID 31724941, 2019). "Our previous studies suggested an important role for PPARα in anti-oral cancer activity in both animal and cell culture models." (PMID 31724941, 2019). "At the same time, they investigated the role of PPARα in the fibrate-dependent metabolic changes of the oral cancer cell line." (PMID 29966227, 2018). "It was reported that the administration of fenofibrate (a PPARα agonist), on cell lines and a mouse model of oral cancer, supported hexokinase II and VDAC (voltage-dependent anion channel) dissociation." (PMID 29966227, 2018). "Activation of PPARα by fenofibrate decreased the migration ability of oral cancer cells in vitro and suppressed the tumor progression into squamous cell carcinoma in vivo." (PMID 26869356, 2016). "Our results showed that PPARα expression was negatively correlated with tumor progression in an oral cancer mouse model." (PMID 26869356, 2016). "Our results indicate that PPARα exhibits a great potential for anti-oral cancer therapies by modulating cancer cell mitochondrial energy metabolism." (PMID 26869356, 2016). "HMGCS2 may promote the metastasis of CRC and oral cancer cells in a ketogenesis enzymatic-independent manner via HMGCS2/PPARα/Src axis activation." (PMID 32155177, 2020). "In conclusion, next-generation sequencing analysis revealed that a total of 13 genes (RRP43, RRP42, CSL4, TRF4, Mtr4, RRP6, MPP6, CNOT2, CNOT3, SKI2, Ski3, EDC4, and XRN1) involved in the mRNA degradation pathway were upregulated by PPARα activation in oral cancer cells." (PMID 31724941, 2019). "Nevertheless, the identification of PPARα-targeted genes in the RNA degradation pathway may help to highlight treatment strategies for oral cancer." (PMID 31724941, 2019). "Activation of PPARα through fenofibrate suppressed migration of oral cancer cells." (PMID 26869356, 2016). "Therefore, we suggest that the activation of PPARα to enhance the mRNA degradation pathway might provide a new strategy for oral cancer therapy." (PMID 31724941, 2019). "Glycolysis is obstructed by the PPARα-dependent destruction of the hexokinase II/VDAC complex, leading to metabolic switch and high OXPHOS levels, as demonstrated in oral cancer cells." (PMID 29966227, 2018).
preeclampsia (12 papers, 2008 to 2024). Preeclampsia is a hypertensive disorder of pregnancy that is characterized by new-onset hypertension with proteinuria presenting after 20 weeks of gestation, and depending on mild or severe forms may initially present with severe headache, visual disturbances, and hyperreflexia. "Several studies have investigated the role of PPARα in preeclampsia." (PMID 36831316, 2023).
thyroid cancer (12 papers, 2017 to 2025). "Furthermore, some PFAS activate peroxisome proliferator-activated receptors, namely PPARα, a known component in the development of thyroid cancers." (PMID 33477829, 2021).
acne (11 papers, 2017 to 2025). An inflammatory process of the sebaceous glands which is characterized by comedones, nodules, papules and/or pustules on the skin. "PPARα and PPARγ were found to stimulate sebum production, stimulate sebocyte proliferation and inhibit terminal differentiation and apoptosis, thereby preventing the release of acne-associated lipids, a property that serves as a rationale for activation of these PPARs in the treatment of acne." (PMID 36552866, 2022). "Moreover, PPARα and γ appeared to be triggered by products of 5-lipoxygenase (5- LOX) which is also believed to be upregulated in acne vulgaris, and some studies have shown that 5-lipoxygenase inhibitors such as zileuton potently diminish acne vulgaris clinical manifestations." (PMID 34466486, 2019).
cervical carcinoma (11 papers, 2014 to 2025). A carcinoma arising from either the exocervical squamous epithelium or the endocervical glandular epithelium. "Collectively, these findings suggest that 9-oxo-ODAs may suppress the proliferation of cervical cancer cells and induce apoptosis via PPARα, but the underlying mechanisms warrant further clarification." (PMID 37932321, 2023).
gestational diabetes (11 papers, 2008 to 2026). Carbohydrate intolerance first diagnosed during pregnancy. "A functional assay confirmed that miR-518d directly targets PPARα by binding to the 3'-UTR of its mRNA in a study that also suggested that increased miR-518d expression in placenta is implicated in gestational diabetes." (PMID 31249556, 2019). "We indicate that diet regulated gene expression of PPARα, NOS, CREB3L3, IRS, and CPT I, altering cellular physiological mechanisms and thus increasing or decreasing the risk of gestational diabetes." (PMID 37799768, 2023). "Nutritional disturbances during intrauterine development can also lead to cardiac dysfunction, potentially via dysregulated AMPK/PPARα signaling and impaired vascular endothelial function in offspring of rats with gestational diabetes." (PMID 37571325, 2023). "The PPARα gene was susceptible to epigenetic modification in the livers of offspring of dams fed a low-protein diet and PPAR expression in the livers of offspring from an animal model of gestational diabetes was found to be modulated by different miRNAs." (PMID 34803741, 2021). "In the placentae of women with an uncomplicated pregnancy or gestational diabetes mellitus, there was a positive correlation between the gene expression levels of PPARα and FGF21 and a tendency for a positive correlation between PPARγ and FGF21." (PMID 25890271, 2015). "In contrast to our previous results in placentae from women with or without gestational diabetes, PPARα expression is not correlated to FGF21 expression." (PMID 25890271, 2015).
osteoarthritis (11 papers, 2008 to 2025). A noninflammatory degenerative joint disease occurring chiefly in older persons, characterized by degeneration of the articular cartilage, hypertrophy of bone at the margins and changes in the synovial membrane. "Impaired autophagy contributed to the aggravated deterioration of osteoarthritis articular cartilage by PPARα deficiency associated with the suppression of ERK and Akt, with an implication that triggering PPARα activation ought to be a potential promising therapeutic target for OA therapy." (PMID 37689723, 2023). "Although the chondroprotection of peroxisome proliferator-activated receptor α (PPARα) activation against osteoarthritis (OA) has been revealed, the regulatory mechanism of PPARα deficiency to aggravate osteoarthritic cartilage deterioration remains unclear." (PMID 37689723, 2023). "For example, fenofibrate, which activates fatty acid β-oxidation via PPARα activation and is used to treat cardiovascular disease, has been shown to protect against cartilage degradation and reduce inflammation in osteoarthritis as a drug with autophagic and senolytic activity." (PMID 35888759, 2022). "We identified that PPARA, BMP7, IL1B, LEP, ITGA5 and SREBP1 protein levels in osteoarthritic chondrocytes were highly correlated with BMI, suggesting the potential role of metabolic-related proteins in the development of osteoarthritis." (PMID 19011694, 2008).
Arthritis (10 papers, 2010 to 2025). Inflammation of a joint. "Our group has reported that chronic arthritis decreases Pparα expression in liver and gastrocnemius, whereas the PPARα agonist fenofibrate improves arthritis-induced body weight loss and gastrocnemius muscle wasting by decreasing atrogenes and myostatin." (PMID 23781298, 2012). "Nevertheless, we found only a single study suggesting that also a PPARα agonist fenofibrate would have anti-inflammatory effects in experimentally induced arthritis." (PMID 23594962, 2013). "There is evidence suggesting that PPARγ and PPARα agonists attenuate experimentally induced arthritis in murine models." (PMID 23594962, 2013). "The dramatic decrease in Pparα expression in soleus by arthritis is in accordance with our previous data, in which gastrocnemius Pparα expression is decreased in arthritic rats and normalized by fenofibrate treatment." (PMID 23781298, 2012). "Pparα expression in the soleus was dramatically decreased by arthritis in the rats treated with vehicle to 8.5% of controls (P<0.01) but not in those treated with fenofibrate." (PMID 23781298, 2012). "Treatment with a peroxisome proliferator-activated receptor-α (PPARα) agonist had similar effects, attenuating the decrease in gastrocnemius weight and fast-twitch myofibre size, and preventing the arthritis-induced increase in atrogin-1 and MuRF1 expression in a rodent CIA model." (PMID 33658022, 2021). "Arthritis decreased soleus weight, cross-sectional area, fiber size, and its Pparα mRNA expression." (PMID 23781298, 2012). "Therefore, the arthritis-induced decrease in Pparα could also contribute to decrease in fatty acid oxidation and to muscle disturbances, whereas its normalization by fenofibrate treatment may modulate soleus mass recovery." (PMID 23781298, 2012).
glomerulosclerosis (10 papers, 2010 to 2025). A hardening of the kidney glomerulus caused by scarring of the blood vessels. "On the other hand, diabetic PPARα knockout mice have more severe kidney dysfunction symptoms, including albuminuria, glomerular sclerosis, and mesangial area expansion." (PMID 36091833, 2022). "PPARα is increased in the kidneys of streptozotocin-induced diabetic mouse model, but when PPARα was genetically deleted, the mice showed adverse effects, including glomerulosclerosis." (PMID 32226789, 2020). "PPARγ agonists inhibit glomerular sclerosis by reducing ANGPTL4 levels, while PPARα reduces ANGPTL4 levels and relieves tubulointerstitial damage." (PMID 32280690, 2020). "In a mouse model of age-related renal injury, SIRT1/AMPK and PPARα signaling were downregulated, while resveratrol improved the renal function, proteinuria, and glomerulosclerosis by activating NRF2 signaling and activating SIRT1/AMPK and PPARα signaling in the kidney." (PMID 34942962, 2021).
periodontitis (10 papers, 2010 to 2025). An acute or chronic inflammatory process that affects the tissues that surround and support the teeth. "An anti-inflammatory treatment, PPARα agonist, inhibited inflammation and periodontal bone loss in ligature-induced experimental periodontitis." (PMID 35293424, 2022). "Our study shows that PPARα is an essential transcription factor to regulate inflammation and bone loss in the P. gingivalis -associated ligature-induced experimental periodontitis." (PMID 35830121, 2022). "Gingival PPARα decreased and pro-inflammatory cytokines increased in P.gingivalis -associated ligature-induced experimental periodontitis." (PMID 35830121, 2022). "All of these findings support the view that PPARα has a detrimental role in the development of injury associated with periodontitis in rats." (PMID 21253492, 2010). "PPARα agonist inhibited bone loss in a ligature-induced experimental periodontitis mouse model." (PMID 35293424, 2022). "Activation of PPARα downregulated the expression and production of the pro-inflammatory cytokines, and inhibited the alveolar bone loss, which represents a new therapeutic target to treat periodontitis." (PMID 35830121, 2022). "Whether PPARα has a similar pathogenic role in human patients with periodontitis is unclear and must be addressed." (PMID 35830121, 2022). "Our study assessed the pathogenic role of PPARα in periodontitis." (PMID 35830121, 2022). "Our study shows the association between PPARα and the periodontitis cytokines." (PMID 35830121, 2022). "Our goal is to elucidate the molecular pathways through which PPARα activation reshapes macrophage function in periodontitis." (PMID 41124421, 2025). "PPARα agonist reduced TRAP-positive cells in a ligature-induced experimental periodontitis mouse model." (PMID 35293424, 2022). "Then we examined the expression of gingival PPARα and pro-inflammatory cytokines in periodontitis WT mice." (PMID 35830121, 2022). "This study, investigating the effect of fenofibrate, a PPARα agonist, on inflammatory response and bone protection in a ligature-induced experimental periodontitis model, aimed to explore a new therapeutic target as an alternative strategy for periodontitis." (PMID 35293424, 2022). "Hypermethylation was found in TLR regulators genes: MAP3K7, MYD88, IL6R, RIPK2, FADD, IRAK1BP1, and PPARA in early stages of periodontitis, while advanced stages presented hypomethylation of these genes." (PMID 36233348, 2022). "Gingival mRNA levels of PPARα were significantly decreased in experimental periodontitis in WT mice." (PMID 35830121, 2022). "In this study, we evaluate the anti-inflammatory effect of fenofibrate, a PPARα agonist, in an experimental ligature-induced periodontitis model." (PMID 35293424, 2022). "The same contrary and distinctive direction from the healthy controls for moderate or severe periodontitis was found in one position for PPARA (CpG 2) and for MAP3K7 (primers MAP3K7-02:CpG 3)." (PMID 36233348, 2022). "Then we examined if PPARα has a similar TNFα regulating effect on immune cells under periodontitis conditions." (PMID 35830121, 2022). "PPARα protein level was examined by immunohistochemistry in type-2 diabetic Goto-Kakizaki rats with induced periodontitis." (PMID 28678155, 2017). "When the ligature was removed and the periodontitis solved, the normoglycemic rats presented a threefold increase in the relative expression of PPARα." (PMID 28678155, 2017). "Our most essential finding is that PPARα plays a crucial role in periodontitis." (PMID 35830121, 2022). "We examined the PPARα’s bone protection effect in the periodontitis mice." (PMID 35830121, 2022). "We evidence that the transcriptional level of PPARα decreased in the presence of P. gingivalis in the gingival fibroblasts, gingival epithelial cells, and splenocytes, and decreased in the gingival tissue from experimental periodontitis mice as well." (PMID 35830121, 2022).
periodontitis (continued). "This study suggests that PPARα plays an essential role in periodontitis." (PMID 35830121, 2022). "The bone loss of PPARα KO mice in experimental periodontitis was significantly higher than WT mice and was not reduced by fenofibrate treatment." (PMID 35830121, 2022). "Moreover, PPARα agonist fenofibrate treatment significantly reduced the bone loss in WT mice but not in PPARα KO mice, indicating that PPARα is essential to protect the bone in an experimental periodontitis model." (PMID 35830121, 2022). "Thus, PPARα could participate in the resolution of periodontitis through its antiinflammatory properties, but under diabetic conditions, its upregulation is restrained." (PMID 28678155, 2017). "PPARα agonist decreased gingival mRNA levels of IL-1, IL-6, TNF-α, and RANKL/OPG in ligatures-induced experimental periodontitis." (PMID 35293424, 2022). "Secondly, although TNFα are the main pro-inflammatory cytokines in experimental periodontitis model, other cytokines such as IL-6 and INF-γ must be studied with PPARα activation in the future." (PMID 35830121, 2022). "In this study, we demonstrate that a PPARα agonist, WY14643, exerts beneficial effects in a rat model of periodontitis." (PMID 21253492, 2010). "In this study, we have been unable to determine how TNF-α and IL-6 are regulated by PPARα in periodontitis, i.e., whether via the PPAR response element (PPRE) or via other PPARα target genes." (PMID 35293424, 2022). "Despite many studies reported that PPARα expression was lower in the healthy group and higher in periodontitis and peri-implantitis patients, we have not observed significant changes of PPARβ or PPRAα at the transcriptional level in the P. gingivalis + ligation conditions." (PMID 35830121, 2022). "Unlike PPARα alteration, the level of RXR is unaffected by periodontitis induction, suggesting that PPARα is a potentially therapeutic target for periodontitis." (PMID 35293424, 2022).
Autoimmunity (9 papers, 2011 to 2023). The occurrence of an immune reaction against the organism's own cells or tissues. "The authors' conclusion is that males are less prone to develop Th1-mediated autoimmunity because they have higher T-cell expression of PPARα." (PMID 21760804, 2011). "PPARα expression in CD4+ T cells was found to be higher in male than in female mice, suggesting sex specific role of PPARα in T cells mediated autoimmunity." (PMID 21382489, 2011). "The investigation of PPARα-independent mechanisms of PFAS toxicity also suggests suppression of STAT5B, a transcription factor activated by cytokines and involved in the immune cell development and autoimmunity." (PMID 33804855, 2021).
epilepsy (9 papers, 2018 to 2025). A brain disorder characterized by episodes of abnormally increased neuronal discharge resulting in transient episodes of sensory or motor neurological dysfunction, or psychic dysfunction. "For example, fenofibrate and bezafibrate, PPARα agonists, have been shown to have anticonvulsant properties in pentylenetetrazole and lithium–pilocarpine models of epilepsy." (PMID 37176158, 2023). "Selective PPARα agonists have been proven to raise seizure thresholds in animal models of epilepsy, suggesting their possible repurposing in seizure management in patients." (PMID 34681249, 2021). "Free fatty acids used in epilepsy treatment can reduce IL-1β levels, possibly through activation of PPARα, and the ketogenic diet metabolite βHB reduces inflammation." (PMID 30424795, 2018). "Furthermore, central PPARα regulates neuronal activity through modulation of nicotinic acetylcholine receptors, suggesting PPARα agonists may influence the excitation/inhibition balance relevant to epilepsy." (PMID 41009625, 2025).
glucose metabolism disorders (9 papers, 2005 to 2026). "The most significantly affected networks were ‘glucose metabolism disorder’ and ‘transport of lipids’ and within these networks we identified three transcriptional factors being involved, i.e. FOX A2, CEBPA and PPARA." (PMID 32764569, 2020). "Together, our data demonstrated that AEM intervention significantly improved lipid and glucose metabolism disorder by regulating the glycolysis/gluconeogenesis-TCA cycle and by modulating gene expression levels involved in the PPARα signaling pathway." (PMID 29681858, 2018).